UBE2QL1 (ubiquitin conjugating enzyme E2 QL1)
Description:
Probable E2 ubiquitin-protein ligase that catalyzes the covalent attachment of ubiquitin to target proteins. May facilitate the monoubiquitination and degradation of MTOR and CCNE1 through interaction with FBXW7.
Synonyms: FLJ25076
Tractability: Antibody: its Gene Ontology location is reachable by antibodies, with high confidence.
Gene: Protein-coding gene on chromosome 5 (6,448,859 to 6,496,723, forward strand). Ensembl gene ENSG00000215218.
Subcellular location: Nucleus
Subcellular location (Human Protein Atlas): Nucleoplasm; Plasma membrane
Gene Ontology:
Molecular function: protein binding; ubiquitin conjugating enzyme activity
Biological process: protein polyubiquitination; protein ubiquitination
Cellular component: nucleoplasm; nucleus
Genetic constraint (gnomAD): Loss-of-function variants: 5 observed, 11.85 expected, observed/expected ratio (o/e) 0.42, 90% interval 0.22 to 0.89. The upper end of that interval is the gene's LOEUF score, 0.89, which puts it in group 3 of 6, group 1 being the genes least tolerant of losing a copy. Missense variants: 99 observed, 209.33 expected, observed/expected ratio (o/e) 0.47, 90% interval 0.4 to 0.56. Synonymous variants: 96 observed, 89.56 expected, observed/expected ratio (o/e) 1.07, 90% interval 0.91 to 1.27.
Homologues: Orthologues: chimpanzee UBE2QL1 (100% identical), dog UBE2QL1 (100% identical), macaque UBE2QL1 (100% identical), pig UBE2QL1 (100% identical), mouse Ube2ql1 (99% identical), guinea pig UBE2QL1 (96% identical), tropical clawed frog ube2ql1 (95% identical), zebrafish ube2ql1 (92% identical), Drosophila melanogaster CG4502 (66% identical). Paralogues in human: UBE2Q1 (57% identical), UBE2Q2 (53% identical), UBE2D4 (25% identical), UBE2D1 (24% identical), UBE2D2 (24% identical), UBE2D3 (23% identical), UBE2E1 (21% identical), UBE2E2 (21% identical), UBE2E3 (21% identical), UBE2L3 (19% identical), UBE2L5 (19% identical), UBE2L6 (19% identical).
Diseases named in the same sentence as UBE2QL1 in open-access papers:
UBE2QL1 is named in the same sentence as 8 diseases in open-access papers, as found by Europe PMC text mining. Sharing a sentence is not in itself a finding about the gene and the disease. The quoted sentences say what the papers report.
hepatocellular carcinoma (1 paper, 2021). A malignant tumor that arises from hepatocytes. "Aberrant methylation of UBE2QL1 has been found in HBV-related hepatocellular carcinoma." (PMID 33510822, 2021).
lung carcinoma (1 paper, 2024). "The UBE2QL1 gene (Ubiquitin Conjugating Enzyme E2 Q Family Like 1) (average methylation 30%, p = 0.007) encodes a ubiquitin-conjugating enzyme in lung cancer cells." (PMID 38791918, 2024).
tumor (5 papers, 2013 to 2024). "There is a very limited literature for UBE2QL1 in malignancy; however one study ascribes a tumor suppressor function to UBE2QL1 which could be seen as consistent with its down-regulation in the context of more aggressive malignancy." (PMID 26893359, 2016). "Based on the known tumor suppressor function of FBXW7 and the previous report of an RCC associated constitutional translocation that disrupts FBXW7, we suspect that UBE2QL1 inactivation compromises FBXW7 function although further studies are required to elucidate the exact mechanism." (PMID 24000165, 2013). "There are a further eight tumor-suppressor genes (DLEU2, CDKN2C, SPRY4, UBE2QL1, LIN9, TFPI2, LRIG3, DUSP1) and six genes serve as both oncogenes and tumor-suppressor genes (FOXO1, CAV1, KLF6, CDK6, PLK1, CTGF)." (PMID 30563222, 2018). "UBE2QL1 mRNA expression data were available for eight RCC cases with promoter region hypermethylation and each tumor demonstrated ≥60% reduction in expression compared with matched normal tissue." (PMID 24000165, 2013). "Moreover, UBE2QL1 and LINC0528 form a tumor microenvironment that supports cancer development, growth, and progression." (PMID 38791918, 2024).
UBE2QL1 also shares sentences with these, for which no sentence is quoted: cancer (1 paper); Cerebellar hypoplasia (1); gastric cancer (1); hypospadias (1); oncocytomas (1).